IGF2 (insulin like growth factor 2)
Diseases named in the same sentence as IGF2 in open-access papers (continued):
Sharing a sentence is not in itself a finding about the gene and the disease.
breast carcinoma (continued). "When breast cancer cells were exposed to IGF2, cell growth was accelerated and apoptosis induced by paclitaxel was prevented." (PMID 28523716, 2017). "There are yet no known studies to characterize the role of IGF2 action in melanoma but some isolated studies have pointed at a tumor suppressing role of IGF2 in mammary carcinoma cells expressing IGF2R." (PMID 28223541, 2017). "In conclusion, the results illustrated that in CD44+Fbs, binding of IGF2BP3 and CD44 promotes IGF2 expression and then accelerates breast cancer cell proliferation, survival and induced chemotherapy resistance likely by activating Hedgehog signal pathways." (PMID 28523716, 2017). "Our further research for the molecular mechanism showed that IGF2BP3 bound to CD44 mRNA and enhanced CD44 expression, which increased IGF2 levels of fibroblasts and then stimulated breast cancer cell proliferation and drug resistance." (PMID 28523716, 2017). "A major mechanism of resistance to anti-IGF-1R drugs involves the IR, which is commonly overexpressed in breast cancer and predominantly expressed as the so called ‘fetal isoform’ (IR-A), which is a bona fide receptor for IGF-2 and proinsulin." (PMID 28591735, 2017). "Previous reports showed that IGF2 expression enhanced in basal cell carcinoma and breast cancer stroma 12, 13, which suggests IGF2 plays important roles in breast cancer microenvironment." (PMID 28523716, 2017). "According to these findings, DDR1 enhanced breast cancer cell proliferation, invasion and colony formation in response to insulin and IGF-2." (PMID 28591735, 2017). "Significantly, the IR-A/IGF-2 autocrine loop plays a key role in many cancer histotypes, including breast cancer." (PMID 28591735, 2017). "IR overexpression and in particular IR-A isoform upregulation, as well as hyperinsulinemia and IGF-2, have a well-established role in breast cancer both in vitro and in vivo." (PMID 28591735, 2017). "Compared to MMTV‐Her‐2 transgenic mouse mammary tumors, H1047R tumors showed increased upregulation of Wnt/β‐catenin/Axin2, hepatocyte growth factor (Hgf)/Stat3, insulin‐like growth factor 2 (Igf‐2), and Igf‐1R pathways." (PMID 28296140, 2017). "While epithelial breast cancer cells commonly overexpress IGF-1R, surrounding tumor-associated stroma provides a rich source of IGF-2." (PMID 27765027, 2016). "Lastly, the expression of HMGA1P7 was significantly correlated with H19 and IGF2 levels in human breast cancer thereby suggesting a role for HMGA1P7 deregulation in this neoplasia." (PMID 27874091, 2016). "IGF-2 expression is strongly enhanced in invasive breast cancers and stimulates downstream mTOR signaling and TNBC cell migration." (PMID 25874233, 2015). "A large body of evidence indicates the insulin/insulin-like growth factor (IGF-1, IGF-2) pathway in breast cancer progression." (PMID 25874233, 2015). "IGF-2 is detected in both tumor stroma and epithelial breast cancer cells and correlates with both breast epithelial and stromal cell proliferation." (PMID 25874233, 2015). "We are currently investigating signaling mechanisms by which TCDD regulates gene expression in human breast cancer cells stimulated with adipokines or IGF2." (PMID 25699021, 2015). "Adipo-CM-stimulated breast cancer cell proliferation was inhibited with anti-IGF2 blocking antibody." (PMID 25699021, 2015). "Taken together, these data suggest that TCDD inhibits adipo-CM and IGF2 signaling in breast cancer cells by downregulating the expression of genes that are important for sustaining high rates of proliferation." (PMID 25699021, 2015). "Our recent findings indicate that AHR responds to and mediates IGF2 signaling in MCF7 breast cancer cells." (PMID 25699021, 2015). "IGF-2 expression is strongly enhanced in invasive breast cancers and downstream mTOR signaling is stimulated as is TNBC cell migration." (PMID 25874233, 2015).
breast carcinoma (continued). "Under normal conditions, IGF-2 is tightly bound and sequestered, but overexpression of IGF-2 is associated with breast cancer development and increased tumor formation." (PMID 25874233, 2015). "We found that TCDD inhibits adipo-CM- or IGF2-stimulated breast cancer cell proliferation and reduces the expression of E2F1, CCND1, MYB, SRC, JAK2, and JUND1 compared with vehicle." (PMID 25699021, 2015). "IGF-1 and IGF-2 are strong mitogens in a variety of cancer cell lines, including breast cancer, colon cancer, prostate cancer, and myeloma." (PMID 25424625, 2014). "The critical pathway by which IGF-1 and IGF-2 stimulate breast cancer cell proliferation is the PI3K pathway that leads to increases in AKT activity." (PMID 24171117, 2013). "In summary, we provide evidence that adipocyte secreted IGF-2 is sufficient to contribute to the proliferation of human ER expressing breast cancer cells." (PMID 24171117, 2013). "Using highly specific AHR agonists and AHR-siRNA, we provide the first evidence suggesting that specific ligand activation of the AHR inhibits adipo-CM and IGF-2-stimulated proliferation of ER positive human breast cancer cells." (PMID 24171117, 2013). "Using highly specific AHR ligands and AHR short interfering RNA (AHR-siRNA), we show that specific ligand-activated AHR inhibits adipocyte secretome and IGF-2-stimulated breast cancer cell proliferation." (PMID 24171117, 2013). "We provide evidence that adipocytes secrete insulin-like growth factor 2 (IGF-2) at levels that stimulate the proliferation of human estrogen receptor (ER) positive breast cancer cells." (PMID 24171117, 2013). "Ito and colleagues reported lower IGF2 DMR0 methylation levels in 13 of 22 mammary tumor samples compared with histologically normal breast tissue from the same patient, with 7 tumor samples displaying less than 35% methylation." (PMID 23409079, 2013). "Further studies are required to explore the role of IGF-2 in breast cancer development and progression." (PMID 22662119, 2012). "For example, there is monoallelic expression of insulin-like growth factor 2 (IGF2) in normal breast tissue and in all but two cases of breast cancer." (PMID 22929229, 2012). "Rank correlation analysis showed that the expression of IGF-2 in breast cancer tissue was positively correlated to tumor histological grade, lymph node metastasis and the expression of oestrogen receptor." (PMID 22662119, 2012). "Preliminary experiments showed that an H19 antisense transcript, called the 91H RNA, that controls IGF2 gene expression in human breast cancer cells is conserved in the mouse." (PMID 22662250, 2012). "In benign breast lesions, breast cancer and tumor-adjacent tissue, IGF-2 was mainly expressed in the cytoplasm, but its expression rate was different (p<0.05)." (PMID 22662119, 2012). "IGF-2 is involved in the development of breast cancer, and its expression varies in different tissues (benign breast lesions, breast cancer and tumor-adjacent tissue)." (PMID 22662119, 2012). "Immune-histochemical method was used to inspect the expression of IGF-2 in different tissues (benign breast lesions, breast cancer and tumor-adjacent tissue)." (PMID 22662119, 2012). "For instance, circulating IGF2 levels associate with increased risk of ER-positive breast cancer, while tissue HGF overexpression correlates with lymph node metastasis and serves as a prognostic indicator in breast cancer." (PMID 40804939, 2025). "CCND1-driven and IGF2-driven breast cancer have been widely reported." (PMID 39872660, 2024). "Insulin-like growth factor-2 (IGF2) expression is known to be associated with the development of various cancers, including breast cancer, and patients with BWS with specific subtypes of molecular defects are known to show characteristic clinical features and IGF2 overexpression." (PMID 38514513, 2024). "In turn, IGF2 and IRS1 are significantly associated with poor prognosis in breast cancer patients." (PMID 38474285, 2024).
breast carcinoma (continued). "Furthermore, the single-cell RNA-Seq (scRNA-Seq) analysis of breast cancer (BRCA) revealed increased T cell infiltration in tumors with low IGF2 expression compared with those with high IGF2 levels." (PMID 39545420, 2024). "In addition, pericytes-secreted insulin-like growth factor 2 (IGF2) was found to have a very significant pro-proliferative effect on mammary carcinoma." (PMID 37190188, 2023). "In addition, silencing IGF2 signaling or inhibiting IGF2 signaling with matrine (PPP) can block the promoting effect of PCs on breast cancer cell proliferation." (PMID 37666813, 2023). "Furthermore, as high levels of IGF2 have been linked to a poorer prognosis in breast cancer and we find that IGF-II drives proinvasive autocrine signaling in breast cancer cells, this opens up a new avenue for therapeutic intervention through IGF-II depletion." (PMID 37436978, 2023). "In addition, it has been shown in vivo, in TN mammary tumor specimens, that IGF2, together with ERβ1, is significantly expressed in TNBC." (PMID 38069080, 2023). "It has been reported that breast cancer-secreted miR-122 reprograms lung fibroblast aerobic glycolysis and thus promotes metastasis, and it was discovered that cancer cell-secreted IGF2 instigates fibroblasts and bone marrow-derived vascular progenitor cells to promote cancer progression." (PMID 35651785, 2022). "For example, it has been reported that breast cancer-secreted miR-122 reprograms glucose metabolism to promote metastasis; meanwhile, it has been illustrated that cancer cell-secreted IGF2 instigates fibroblasts and bone marrow-derived vascular progenitor cells to promote cancer progression." (PMID 35651785, 2022). "This suggested that HOXC10, FXYD1, MT1X, and IGF2 may play an important role in the development of luminal A breast cancer under the regulation of HOXC-AS3, AC020907.2, AC026461.1, and AC132217.1." (PMID 35692369, 2022). "This suggests that IGF2 plays an important role in the development of HER2-positive breast cancer." (PMID 34837929, 2021). "Thus, our data indicated that IRS1 and IGF2 were functionally interdependent to control Herceptin sensitivity in HER2-positive breast cancer cells." (PMID 33976188, 2021). "Notably, the involvement of secreted IGF2 in metastasis has recently been reported by a study that analyzed brain pericytes producing IGF2 and promoting metastasis of breast cancer to brain." (PMID 34100888, 2021). "A study conducted by Vella and colleagues demonstrated that the IGF2/insulin/IR-A/PI3K/MAPK axis contributes substantially to energetic metabolic phenotype of breast cancer MCF-7 cells by increasing glycolytic activity, mitochondrial functions and cell bioenergetics." (PMID 33673232, 2021). "In the validation cohort, we found that serum IGF2 levels were significantly higher in poor response group than that in good response group among HER2 positive breast cancer patients, which were consistent with the results of postoperative immunohistochemistry report in tumor tissues." (PMID 34837929, 2021). "We performed an analysis of IGF2 expression in breast cancer tissues through TCGA databases." (PMID 34837929, 2021). "Furthermore, addiction to the IGF2-Id1-IGF2 circuit is essential for maintenance of the breast cancer stem-like cells." (PMID 32410828, 2020). "Interestingly, the MDA-MB-231 breast cancer cells (CA) expressed the second highest levels of total IGF2 protein even though it represented only 50% of the IGF2 mRNA when compared to the CRL2335 (AA) cell line." (PMID 33216823, 2020). "In addition, IGF2 expression is reported to be suppressed by miR-100 and miR-125b in breast cancer and C2C12 immortalized mouse myoblast cells." (PMID 33293585, 2020). "Thus, recent studies demonstrate that INSR isoform-A modulates metabolic reprogramming of breast cancer cells in response to both IGF2 and indulin stimulation." (PMID 31771180, 2019).
breast carcinoma (continued). "Understanding the mechanisms of IGF2/ERβ axis in TNBC tumors could provide an opportunity to target this aggressive subtype of breast cancer." (PMID 30338035, 2018). "Importantly, we found that IGF2 secretion from CD44+Fbs activates Hedgehog signal pathway to increase breast cancer cell growth and induce drug resistance." (PMID 28523716, 2017). "When MCF‐7 and SKBR3 cells were treated with IGF2, the cell apoptosis rates decreased compared with the cells with paclitaxel treatment, which suggested that IGF2 could protect breast cancer cell from apoptosis induced by paclitaxel MCF‐7 and SKBR3 cells." (PMID 28523716, 2017). "In our study, we found that IGF2 could activate Hedgehop signal pathway in the breast cancer cells in the presence of CD44+Fbs." (PMID 28523716, 2017). "IGF2 was found to activate Hedgehog signal pathway in breast cancer cells." (PMID 28523716, 2017). "We next evaluated whether DDR1 expression could modulate the biological effects of insulin and IGF-2 in breast cancer cells." (PMID 28591735, 2017). "This indicated that CD44+Fbs could promote breast cancer cell proliferation and drug resistance by activating Hedgehog pathway via IGF2 secretion." (PMID 28523716, 2017). "Thus, the IR–DDR1 crosstalk constitutes a positive feedback loop enhancing the effects of insulin and IGF-2 in breast cancer cells." (PMID 28591735, 2017). "The study suggests that CD44 and IGF2 are potential targets for breast cancer therapy." (PMID 28523716, 2017). "It is reported that IGF2 was up‐regulated in breast cancer stroma 12, 13, 14; however, its role and molecular mechanism in the crosstalk between fibroblasts and cancer cells are still unknown." (PMID 28523716, 2017). "So, we used IGF2 to treat breast cancer cells to observe cell proliferation and drug resistance." (PMID 28523716, 2017). "Autocrine produced hGH and hPRL could presumably also exert IGF1 and IGF2 independent oncogenic effects in HCC as has been previously reported for mammary carcinoma cells." (PMID 27102295, 2016). "Altogether, these results strongly support the idea that HMGA1P7 could act as ceRNAs in human breast cancer and represent a novel potential mechanism accounting for H19 and IGF2 upregulation in these tumors." (PMID 27874091, 2016). "Westley and May also report that estrogen signaling may cross communicate with IGF pathways, with estrogen promoting increased breast cancer production of IGF-2." (PMID 25874233, 2015). "Human colon cancer cells (HRT-18 and HT-29) were with loss of imprinting of IGF2 gene (LOI), and the human colon cancer cells (HCT-116), breast cancer cells (MCF-7) and human gastric epithelial cells (GES-1) were maintenance of imprinting of IGF2 gene (MOI each)." (PMID 23900345, 2013). "A small number of studies have investigated IGF2 methylation in breast cancer." (PMID 23409079, 2013). "Whether IGF2 may be a peripheral blood marker of breast cancer remains to be established and requires further studies with larger sample sizes." (PMID 23409079, 2013). "Expression of insulin-like growth factor 2 (IGF-2) in breast cancer." (PMID 22662119, 2012). "The comparison of IGF-2 expression in breast cancer and the adjacent tissues." (PMID 22662119, 2012). "In clinical research, we found that decreased miR-98-5p level or increased IGF2 level significantly associated with poor treatment response and poor overall survival (OS), poor recurrence free survival (RFS) and poor distant metastasis-free survival (DMFS) in HER2-positive breast cancer." (PMID 34837929, 2021). "Firstly, IGF2 overexpression could be seen in Herceptin resistant breast cancer cells." (PMID 34837929, 2021). "In this study, we seek to investigate the contributions of IGF2 and the insulin receptor substrate-1 (IRS1) to Herceptin resistance and elucidate the underlying mechanism of increased expression of both IGF2 and IRS1 and aberrant activation of IGF-1R signaling in Herceptin-resistant breast cancer." (PMID 33976188, 2021).
breast carcinoma (continued). "The IGF2 gene was related to breast epithelial and stromal cell proliferation in human, and over-expression of IGF2 increased breast cancer development, thus, it was implied that IGF2 may play an important role in maintaining bovine mammary gland epithelial cell function well." (PMID 28356085, 2017). "IGF2 could modulate breast cancer cell biological behaviours in tumour stroma." (PMID 28523716, 2017). "Therefore, it implies that IGF-2 may have certain significance for the treatment and prognosis of breast cancer." (PMID 22662119, 2012). "While our model system involves increased IGF-1R activity due to receptor overexpression, it must be noted that increased IGF-1R signaling in clinical breast cancer might also arise from mechanisms involving abnormally high IGF-2 expression or from derangements in IGF-binding protein physiology." (PMID 15987464, 2005). "The activation of FOXO3a, triggered by increased IGF2 expression, is modulated by miR-128-3p, miR-30a and miR-193-5p, which target IRS1 and IGF2, maintaining HER2-positive breast cancer cells responsive to trastuzumab." (PMID 41301038, 2025). "M6PR has been associated with a potential anti-tumor role due to its ability to bind and degrade the mitogen insulin-like growth factor 2 (IGF2), but so far it was mentioned only in connection with breast cancer." (PMID 40649716, 2025). "The long noncoding RNA SNHG16 promoted breast cancer cell migration by acting as a competitive endogenous RNA (ceRNA) for E2F5 by binding with miR-98, while the miR-98-5p/IGF2 axis affected herceptin sensitivity in HER2 positive breast cancer." (PMID 38872210, 2024). "In breast cancer, ASNS is regulated by IGF1/IGF2, affecting amino acid transport, metabolism, protein biosynthesis, and stability." (PMID 38474084, 2024). "Another study found that dihydromyricetin can induce the expression of miR-98–5p and reduce the level of IGF2, thereby reversing the resistance of HER2-positive breast cancer cells to trastuzumab." (PMID 36210846, 2022). "Inhibition of IGF2/IGFR1 signaling pathway markedly enhanced radiosensitivity and radiation induced apoptosis of breast cancers." (PMID 34439387, 2021). "Next, we found that reduction of several FOXO3a-driven miRNAs played a crucial role in upregulation of both IGF2 and IRS1 in Herceptin-resistant breast cancer cells." (PMID 33976188, 2021). "Studies have found that IGF2/IGF-1R/IRS1 signal pathway is normally inhibited through negative feedback to maintain basic cell survival and proliferation in HER2-positive human breast cancer cells." (PMID 34837929, 2021). "Collectively, these data established an essential role for FOXO3a transcriptional regulation of specific miRNAs to control IGF2 and IRS1 expression, thereby altering Herceptin sensitivity in HER2-positive breast cancer cells." (PMID 33976188, 2021). "IGF2-targeting and MDM2-targeting drugs have been in clinical trials for other tumor types, and CDK4/6 inhibitors are already approved for patients with breast cancer." (PMID 34680217, 2021). "For example, the H19/insulin-like growth factor 2 (IGF2) and insulin-like growth factor 2 receptor (IGF2R) imprinted gene network is involved in colorectal, prostate, lung and breast cancers." (PMID 32448196, 2020). "Several growth factor–related breast cancer genes (EGF, IGF1, IGF1R, IGF2, IGFBP3, IL10, TGFB1, and VEGF), including 26 SNPs, were used as simulation data to evaluate existing algorithms and the proposed HTGA." (PMID 32554381, 2020). "In breast cancer cells, blocking either IGF-2 or the IR markedly inhibited growth, demonstrating the relevance of the IR-A/IGF-2 loop in cell growth." (PMID 30453495, 2018). "Significantly, we have previously shown that IGF-1, IGF-2 and insulin induce DDR1 upregulation in breast cancer cells by activating the AKT/miR199a-5b pathway." (PMID 28591735, 2017).